AR (androgen receptor)
Diseases named in the same sentence as AR in open-access papers (continued):
Sharing a sentence is not in itself a finding about the gene and the disease.
metastatic carcinoma (23 papers, 2007 to 2025). A carcinoma which has spread from the original site of growth to another anatomic site. "PPP2R1A (E370X), SETD2 (I1608V), SMAD4 (G382T), and AR splicing site mutations were specific to liver metastatic cancer." (PMID 27023146, 2016). "The AR-V7 gene, associated with resistance to AR-targeting agents in patients with mCRPC, was only detected in metastatic cancer patients and displayed twice the detection rate, with an expression level that was 10 times higher for the CTC-μChip than for the AdnaTest." (PMID 32961814, 2020). "The gene HPN has been associated with tumor invasion and metastasis, while the androgen receptor (AR) gene is crucial in promoting metastatic cancer progression." (PMID 40034593, 2025). "AR, ER, and PR expressions are seen in a high number of endometrioid and metastatic carcinomas (97%-100%) and their positivity are very similar." (PMID 37725629, 2023). "Among the three micro-RNAs that we selected, miR-21 is known to function in cell proliferation and relate to cancers; miR-221 is known to regulate the cell cycle; miR-141 is known to affect the expression of androgen receptor and progress of metastatic cancer." (PMID 34972164, 2021). "Analysis of the TCGA-PRAD and SU2C-PRAD datasets indeed revealed that MAO-A mRNA expression is significantly positively correlated with AR activity, similar to observed GR activity in primary and metastatic cancer." (PMID 33795839, 2021). "Thousands of metastatic cancer patients are undergoing multiple forms of androgen/AR-blockade treatments, e.g., standard ADT/castration, or the next-generation drug enzalutamide." (PMID 30478344, 2018). "In combination, the inhibition of MET-mediated pSTMN1S16 and AR activity could significantly advance the treatment of metastatic cancers." (PMID 40723207, 2025). "However, in a few cases, the tumor adapts to AR suppression through persistent activation of AR signaling without ligand or complete elimination in AR expression, leading to recurrent and metastatic cancer." (PMID 34681904, 2021). "Axillary lymph node biopsy showed metastatic carcinoma with IHC: ER 90% (3+), PR 90% (3+), HER2 (c-erbB-2) 1+, Ki-67 20%, and AR 90% (3+)." (PMID 40548112, 2025). "Internalizing SHALs targeting under-glycosylated MUC1, the androgen receptor and other tumor specific cell surface proteins that residualize the radioisotopes they carry could also be developed as small molecule therapeutics for a wide variety of other types of metastatic cancer." (PMID 19383174, 2009). "The status of AR, ER, and PR expression were evaluated in 71 cases which were categorized into endometrial endometrioid cancer (EEC), non-endometrioid endometrial cancers (NEEC), and metastatic carcinomas of endometrium." (PMID 37725629, 2023).
thyroid cancer (23 papers, 2014 to 2026). "While there is a paucity of such studies on thyroid cancer, it would be worthwhile to investigate any AR splice variant that leads the tumorigenesis of PTC and ATC." (PMID 37190127, 2023). "In thyroid cancer, the loss of the AR is closely associated with the progression of thyroid cancer." (PMID 40729027, 2025). "Our studies provide evidence that the induction of senescence is a novel function of AR activation in thyroid cancer cells and may underlie the protective role of AR activation in the decreased incidence of PTC cancer in men." (PMID 37190127, 2023). "Our studies provide evidence that the induction of senescence is a novel function of AR activation in thyroid cancer cells, and may underlie the protective role of AR activation in the decreased incidence of TC in men." (PMID 37190127, 2023). "In addition, miR-124a is considered to be a potential factor underlying the gender-specific expression of AR in thyroid cancer." (PMID 35163477, 2022). "Likewise, decreased expression of AR in thyroid carcinoma was associated with poor prognosis and more aggressive tumor behavior." (PMID 33778495, 2021). "This supports our previous observation, and further suggests a potential role of AR inactivation in thyroid cancer etiology." (PMID 37190127, 2023). "With the observance of a non-inflammatory SASP in our model, we determined the migration and invasion potential of AR-induced senescent thyroid cancer cells." (PMID 37190127, 2023). "Further, we describe an anti-proliferative facet of the androgen receptor in the thyroid cancer cell lines 8505C and K1, which we engineered to express a functional AR gene to render it androgen-responsive (84E7, 8505C-lentiAR, and K1-lentiAR)." (PMID 37190127, 2023). "The higher incidence of TC in women focused our attention on the potentially protective role of androgens and androgen receptor activation in thyroid cancer." (PMID 37190127, 2023). "In vitro studies on undifferentiated thyroid cancer cells demonstrated that hormonal activation of androgen receptor with dihydrotestosterone addiction led to receptor translocation into the nucleus, proliferation reduction, and a shift towards G1 arrest." (PMID 37635968, 2023). "As thyroid cancer cell lines rarely express functional androgen receptors, the anaplastic thyroid cancer cell line, 8505C, was stably transfected with an AR cDNA plasmid, and a clone, 84E7, was used for further analysis." (PMID 37190127, 2023). "Exploration into the modulation of crosstalk between androgen/AR complex and these signaling pathways through androgen manipulation in thyroid cancer merits future research." (PMID 37190127, 2023). "We show that androgen stimulation of the androgen receptor inhibits the growth of thyroid cancer cells by inducing a state of senescence, in which cells are not killed, but are unable to multiply." (PMID 37190127, 2023). "Experimental analysis confirmed that miR-124a determined the expression pattern of the AR gene in thyroid cancer tissues." (PMID 35163477, 2022). "In another study, Stanley described sex differences in testosterone levels and androgen receptor expression in human thyroid carcinoma, claiming a specific sex modulation of androgen in thyroid tumors." (PMID 35113037, 2022). "In summary, this study suggests that PD-L1 is downregulated by androgens in thyroid cancer cells in an AR-dependent mechanism." (PMID 34422798, 2021). "While the 8505C cell line expresses relatively high levels of AR compared to other thyroid cancer cell lines, it is evident from our results that these cells do not respond to DHT stimulation." (PMID 34422798, 2021). "Further investigation into the role of AR in primary thyroid cancer cells, particularly PTC cells, is warranted to establish a potential underlying mechanism and its role in the disparity in incidence." (PMID 34422798, 2021).
thyroid cancer (continued). "The undifferentiated thyroid cancer cell line, 8505C, was used due to the high surface level expression of PD-L1 and higher AR expression relative to other thyroid cancer cell lines based on mRNA-sequencing and protein array data in the CCLE." (PMID 34422798, 2021). "In this study, we present data that suggest that AR activation attenuates PD-L1 expression in a thyroid cancer cell line, potentially by inhibiting NF-kB signaling by increasing the IkBα inhibitory subunit." (PMID 34422798, 2021). "AR expression in both the NYMC RNA-seq dataset and TCGA Thyroid Carcinoma project’s RNA-sequencing dataset showed significant (p < 0.0001) reduction in AR expression in tumors compared to normal tissue." (PMID 34422798, 2021). "Given the fact of NCOR1 as AR suppressor in PCa progression and an oncogenic role in thyroid cancer, it is reasonable for NCOR1 to act as both oncogene and tumor suppressor." (PMID 33058520, 2020). "We found that AR mRNA expression was significantly lower in the thyroid cancer cell lines BCPAP and TPC-1 than in the normal human thyroid cell line Nthy-ori-3-1." (PMID 32365531, 2020). "AR protein expression was significantly lower in thyroid cancer tissue than in paired normal tissue, both overall and in men and women separately (p < 0.05 each)." (PMID 32365531, 2020). "Despite high AR expression in thyroid cancer, there are only anecdotal reports of therapeutic hormonal manipulation [S16]." (PMID 25595907, 2015). "Disrupted regulation of AR signaling has been described in the development and progression of multiple cancers including testicular cancer, breast, and thyroid cancer." (PMID 24922532, 2014). "Thyroid is also known to express AR in benign and malignant tissue, and AR is known to play a significant role in thyroid cancer development, with higher AR concentration, malignancy rate, and poorer prognosis in males than females." (PMID 24922532, 2014). "Regulation of AR by various coregulators has been observed in testicular, prostate, bladder, breast, and thyroid cancer." (PMID 24922532, 2014). "Finally, androgen stimulation of the androgen receptor suppresses the growth of thyroid cancer cells, potentially accounting for the lower incidence in men." (PMID 39951481, 2025). "Similarly, AR was negatively correlated with PD-L1 in thyroid cancer, where AR reduced PD-L1 promoter activation by NF-kβ signaling." (PMID 40612952, 2025). "AR-mediated PD-L1 downregulation was also reported for thyroid cancer." (PMID 41463239, 2025). "Further, androgen receptor expression is decreased in thyroid cancer cells." (PMID 37190127, 2023). "Furthermore, the activation of the androgen receptor (AR) triggers cellular senescence in thyroid cancer cells." (PMID 37924384, 2023). "We investigated the convergence of AR signaling with senescence pathways in a thyroid cancer model." (PMID 37190127, 2023). "Testosterone levels in serum and thyroid cancer tissues were higher in women and lower in men with thyroid cancers versus related control groups, whereas binding activity and androgen receptor mRNA expression were enhanced in men and reduced in women with thyroid cancers." (PMID 37635968, 2023). "Notably, the DHT-mediated downregulation of PD-L1 was replicated in another thyroid cancer cell line, K1, and stably expressing the pLENTI6.3/AR-GC-E2325 construct." (PMID 34422798, 2021). "Therefore, androgen receptor expression may be involved in ALDH1B1-induced thyroid cancer progression." (PMID 35280765, 2022). "While AR was shown to be a oncogene, it has been shown to have the opposite effect in kidney chromophobe (KICH) and thyroid carcinoma (THCA)." (PMID 33778495, 2021). "High-throughput genomic and proteomic approaches to the study of the interaction between androgen–AR axis and the EMT pathway with cancer stemness may reveal the novel molecular mechanism underlying PTC tumorigenesis and provide useful information to find new therapeutic targets in thyroid cancers." (PMID 32365531, 2020).
thyroid cancer (continued). "The thyroid cancer cell lines, BCPAP and TPC-1, were used to evaluate the effects of AR on the regulation of cell migration, and key epithelial–mesenchymal transition (EMT) markers." (PMID 32365531, 2020). "In contrast, the treatment of 8505C cells (thyroid cancer cells that do not express AR) with DHT did not alter the expression of PD-L1." (PMID 37373038, 2023). "In addition, the treatment of 84E7 cells (AR-expressing thyroid cancer cells) with dihydrotestosterone (DHT), which is an agonist of AR, resulted in the suppression of PD-L1 expression." (PMID 37373038, 2023). "Given the correlation between PD-L1 and AR expression in primary PTC tissue, we designed a series of cell culture experiments to test whether androgens regulate the expression of PD-L1 in thyroid cancer." (PMID 34422798, 2021). "With mRNA and protein expression of USP26 confirmed in breast and thyroid cancer, the interaction of USP26 and AR may play a significant role in tumorigenesis." (PMID 24922532, 2014).
asthma (22 papers, 2007 to 2026). "Specifically, only EGFR (epithelial growth factor receptor) and SMAD genes, both of which are associated with epithelial dysfunction and AR, were upregulated in children whose viral upper respiratory infections progressed to asthma exacerbations." (PMID 38981012, 2024). "Male sex and AR regulation of type 2 immunity has implications for viral infection and secondary links to asthma susceptibility that differs before and after puberty." (PMID 37063266, 2023). "This evidence is supported by the fact that the higher airway expression of AR and higher androgen levels in men are associated with better lung function, fewer symptoms, and a lower fraction exhaled nitric oxide (FeNO) in asthma." (PMID 36038873, 2022). "In summary, our results show that AR signaling increases Treg suppressive function by limiting ST2+ Tregs as a mechanism to decrease airway inflammation associated with asthma." (PMID 35025767, 2022). "This study determined a mechanism by which AR signaling increased Treg suppressive function to decrease airway inflammation associated with asthma." (PMID 35025767, 2022). "The presence of these AR variants was further investigated in placentas during impaired pregnancies associated with maternal asthma." (PMID 34357016, 2021). "Differential methylation patterns have been observed in three genes-androgen receptor (AR), TNFα, and IL-4 causing asthma in children." (PMID 32435260, 2020). "Moreover, in mice and humans, androgen receptor deficiency decreases asthma risk, and children and adults with decreased airway androgen receptor expression have more severe asthma, lower lung function, more inflammation, and worse symptom scores." (PMID 38981012, 2024). "Androgens signaling through AR decreased type 2 and Th17‐mediated airway inflammation while increasing T regulatory (Treg) cell suppressive function in asthma." (PMID 41508394, 2026). "Here, we focus on how androgen signaling through the androgen receptor (AR) alter metabolic pathways critical for Th17 and Th2 cells, cell types important in allergic airway inflammation and asthma." (PMID 39404231, 2024). "Androgen receptor signaling negatively regulates lung inflammation which correlates with increased prevalence of asthma in women; however, the role of sex hormones in driving ILC plasticity in response to infections is yet to be elucidated." (PMID 36838426, 2023). "Our findings showed that AR signaling stabilized Treg suppressive function, providing a mechanism for the sex difference in asthma." (PMID 35025767, 2022). "Defining the mechanisms by which androgens and AR signaling reduce airway inflammation in asthma is critical for the personalization of therapeutics for men and women with asthma and the development of DHEA as a potential therapeutic for asthma." (PMID 35025767, 2022). "Clinical studies showed that the androgen dehydroepiandrosterone (DHEA) reduced asthma symptoms in patients, and mouse studies showed that androgen receptor (AR) signaling decreased allergic airway inflammation." (PMID 35025767, 2022). "HTR2C, CYP1B1, CYP19A1, ESR1, ESR2, PDR, and AR are found to be interrelated to hormonal disorders; ABCC1, NQO1, TIMP1, ADRB2, and ALOX5 are associated with asthma." (PMID 29861771, 2018). "Since the TGFβ2 isoform acts on the same receptors and signal via the same AR-Smads as TGFβ1, these results indicate that TGFβ2 is also a likely candidate to explain activation of Smad signaling in asthma." (PMID 17892594, 2007). "This suggests that oestrogen may promote the expression of PPARγ protein, which in turn may have a role in airway inflammation such as asthma and AR by affecting ILC2s, further revealing a new pathway of action of oestrogen in triggering asthma." (PMID 39800672, 2025). "AR signaling inhibited Treg reactivity during asthma challenge in mouse model." (PMID 40406098, 2025).
asthma (continued). "To determine if AR signaling in CD4+ T cells attenuated allergen-induced airway hyperresponsiveness (AHR) to methacholine, a physiological hallmark of asthma, we measured airway resistance in response to increasing concentrations of nebulized methacholine via Flexivent." (PMID 39404231, 2024). "However, in murine models of asthma after sexual maturity, AR activity decreases effector Th2 and Th17 cells, which correlates with epidemiological data showing that asthma propensity is decreased in males after adolescence." (PMID 37063266, 2023). "Mouse models of house dust mite-induced asthma show that cell intrinsic AR activity attenuated IL-17A+ Th17 cells, leading to a decrease in neutrophil infiltration, while endogenous androgens indirectly decreased the number of pro-inflammatory IL-13+ Th2 cells by suppressing IL-4 production." (PMID 37063266, 2023). "For example, AR (androgen receptor) could be regarded as an understudied, highly connected regulator, which was only recently correlated with asthma control." (PMID 36835202, 2023). "Altered AR signaling in the presence of these isoforms may explain the differential response of developing fetuses to asthma in mothers during pregnancy between males and females." (PMID 34357016, 2021). "As a result, they could be bonded asthma-related proteins, such as AR, FOXA1, GATA3, and GATA6." (PMID 37569643, 2023). "Future research will determine if common pathways are activated or attenuated by intrinsic AR activity in Th1 cells prominent in IFN-centered respiratory virus infections and/or in Th2 and Th17 cells important in asthma and extracellular bacterial infections." (PMID 37063266, 2023). "Furthermore, the activation of AR may exert beneficial effect in asthma by ameliorating airway hyperresponsiveness (AHR) and type 2 inflammation via reducing intracellular calcium influx and modulating complex mechanisms such as the interleukin (IL) 17A pathway." (PMID 36038873, 2022). "Further, we showed that AR signaling in Tregs decreased allergic airway inflammation and AHR, providing additional mechanisms for how AR signaling attenuates asthma pathogenesis." (PMID 35025767, 2022). "AR signalling induced by androgens stabilizes CD4+ regulatory T cells (Tregs) suppressive function, providing a mechanism for higher prevalence of asthma in women compared with men." (PMID 36038873, 2022). "We have published that androgens signaling through the androgen receptor (AR) were important in downregulating allergen‐induced airway inflammation in mouse models as well as increasing lung function, measured with FEV1, in patients with asthma administered the androgen DHEA." (PMID 41508394, 2026). "In this sheep model for maternal asthma there is a decrease in nuclear expression of AR-45 and cytoplasmic expression of V1, proposing that AR-45, not AR-FL, may be responsible for growth." (PMID 37626712, 2023). "However, it is noteworthy to mention that this increased pSmad2 observed in asthma does not exclude the possible involvement of other TGFβ family members in the activation of AR-Smads (Smad2/3)." (PMID 17892594, 2007).